ALKBH5 (alkB homolog 5, RNA demethylase)
Diseases named in the same sentence as ALKBH5 in open-access papers (continued):
Sharing a sentence is not in itself a finding about the gene and the disease.
cancer (continued). "ALKBH5 promotes cancer progression by regulating TIMP3, FOXM1, CDKN1A, JAK2, FOXM1, AURKB, G6PD, HBx, USP1, NANOG, PVT1, IGF1R lncRNA NEAT1, and lncRNA RMRP expression." (PMID 35945641, 2022). "The involvements of METTL3, METTL14, FTO, and ALKBH5 in many cancers have been investigated, and they demonstrate various roles in different cancers." (PMID 35596159, 2022). "The significance of carbohydrate metabolism in cancer has been intensively investigated over the years, but the correlation between ALKBH5 and glucose metabolism in NB remains to be elucidated." (PMID 35517412, 2022). "The reason for the controversial function of ALKBH5 in cancer likely relates to the communication between ALKBH5 with long coding RNAs, miRNAs, mRNAs, etc.." (PMID 35279083, 2022). "An increasing number of studies have found that ALKBH5 plays an important role in cancer progression." (PMID 36028854, 2022). "In this study, we first performed comprehensive bioinformatics analysis to determine the functional role of ALKBH5 in multiple cancers using the patient data from various databases." (PMID 35444654, 2022). "In pancreatic cancer (PC), ALKBH5-mediated m6A modification caused DDIT4-AS1 overexpression, and DDIT-AS1 increased cancer stemness and led to gemcitabine resistance by destabilizing DDIT4 and activating the mTOR pathway." (PMID 36517820, 2022). "The independent studies of different cancer types or studies using different models suggested that the regulatory network of ALKBH5 in cancer varies from case to case." (PMID 35063010, 2022). "Analysis of the genetic expression data from CCLE indicated that METTL16 and ALKBH5 expression levels were lower in PDA cell lines than in most other cancer cell lines." (PMID 36158188, 2022). "Our study novelty found that MAP3K8 can mediate ALKBH5 activation of the classical cancer-promoting pathways ERK and JNK." (PMID 35982895, 2022). "In this study, we performed systematic bioinformatics analysis to determine the biological functions and prognostic significance of ALKBH5 in several cancers using the patient data in multiple databases." (PMID 35444654, 2022). "Inhibitors of these regulators, like DNA methylation inhibitor 5-azacytidine (5-aza) and histone acetyltransferase EP300 inhibitor C646, as well as miRNA miR-193a-3p mimic are able to indirectly or directly suppress ALKBH5 expression in cancer cells." (PMID 35063010, 2022). "The crosstalk between ALKBH5 and ncRNAs appears to form a feedback loop with extensive impacts in cancers." (PMID 35063010, 2022). "ALKBH5, the second identified m6A demethylase, has been found to play a critical role in various cancer-related characteristics, such as autophagy, stem cell self-renewal, radioresistance and anti–PD-1 therapy response." (PMID 35579750, 2022). "The m6A demethylase activity of ALKBH5 plays roles in the promotion of certain cancers, including glioblastoma, hepatocarcinoma, and acute myeloid leukemia." (PMID 35333330, 2022). "These ALKBH5 regulators, including multiple epigenetic modulators, transcription factors and non-coding RNAs, are also dysregulated in specific cancers and exert similar effects on cellular phenotypes as ALKBH5." (PMID 35063010, 2022). "ALKBH5, a demethylated enzyme, has been shown to participate in various biological processes of human cancer, such as growth and metastasis." (PMID 36376862, 2022). "The pan-cancer analysis showed correlation between ALKBH5 mRNA expression and the prognosis of cancer patients." (PMID 35444654, 2022). "The application of gene therapy to restore ALKBH5 expression in cancers as well as its clinical efficacy and biosafety await further validation." (PMID 35063010, 2022).
cancer (continued). "For instance, m6A demethylases, such as FTO and ALKBH5, was shown to be essential for glioblastoma cancer stem cells and they mediate resistance to conventional chemotherapy and cancer recurrence in, respectively." (PMID 35884552, 2022). "We also discussed the therapeutic implications of targeting ALKBH5 in cancer and potential ALKBH5-targeting strategies." (PMID 35063010, 2022). "Several additional studies have uncovered a regulatory function of ALKBH5 in cancer cell proliferation, invasion and metastasis." (PMID 35579750, 2022). "HE staining further confirmed obvious cancer metastasis in the lung tissues of mice treated with oe-ALKBH5 + sh-NC, whereas the metastasis was decreased in the presence of oe-ALKBH5 + sh-UBE2C." (PMID 36551544, 2022). "HE staining results revealed that Exos-sh-NC improved the cancer metastasis in the lung tissues of mice, and Exos-sh-ALKBH5 led to more evident improvement." (PMID 36551544, 2022). "The Cancer Cell Line Encyclopedia (CCLE) dataset also revealed that ALKBH5 was highly expressed in MM compared with other cancer cell lines." (PMID 34759347, 2022). "A number of previous studies have demonstrated that ALKBH5 exerts a cancer-promoting effect in glioblastoma, osteosarcoma, colon cancer, ovarian cancer, esophageal squamous cell carcinoma, endometrial cancer, and renal cell carcinoma." (PMID 35318440, 2022). "ALKBH5 is involved in the biological progression of a variety of cancers, where it plays an important role." (PMID 35945641, 2022). "Here we reviewed up-to-date findings about the pathological roles of ALKBH5 in cancer, the molecular mechanisms by which it exerts its functions, as well as the underlying mechanism of its dysregulation." (PMID 35063010, 2022). "For example, YAP1, a transcription co-activator whose activation is important for cancer cell proliferation, survival, migration and invasion, is one of the critical targets that mediate ALKBH5’s function in multiple cancers." (PMID 35063010, 2022). "Firstly, we evaluated the correlation between ESTIMATE scores (ESTIMATE, immune, and stromal scores) and ALKBH5 expression levels in pan-cancers." (PMID 35444654, 2022). "In HCC, ALKBH5 suppresses the proliferative and invasive properties of cancer cells by m6A-mediated inhibition of LYPD1." (PMID 35063010, 2022). "We identified amplifications, mutations, and deep deletions as the most frequent alterations in the ALKBH5 gene in several cancer types." (PMID 35444654, 2022). "The finding of upstream regulators of ALKBH5 in cancers provides an alternative approach to inhibit ALKBH5 by targeting its regulatory machinery." (PMID 35063010, 2022). "ALKBH5 is another major m6A demethylase which plays a critical biological and pharmacological role in human cancer." (PMID 35784761, 2022). "Particularly, the presence or absence of other regulatory partners are likely to be critical confounding factors that change the role of ALKBH5 in cancer." (PMID 35063010, 2022). "Remarkably, when comparing BlCa with NUT, we found that not only METTL14 but also METTL3, VIRMA, and ALKBH5 expression was significantly decreased in cancer tissues." (PMID 35048498, 2022). "Increasing research has focused on exploring the mechanisms responsible for the dysregulation of ALKBH5 in cancer." (PMID 35063010, 2022). "To evaluate the expression of ALKBH5 in cancers, we initially detected mRNA expression of ALKBH5 in 23 solid cancers in TCGA (The Cancer Genome Atlas) datasets." (PMID 35979628, 2022). "ALKBH5, a demethylase, is well known to be involved in the occurrence and development of various cancers." (PMID 36397058, 2022). "As m6A demethylase, FTO and ALKBH5 were reported to play critical roles in multiple cancers and are involved in cancer drug resistance." (PMID 34745970, 2021).
cancer (continued). "To date, a key set of studies have shown controversial roles of ALKBH5 in OC, which have also been observed in other cancer studies." (PMID 34895230, 2021). "Available pieces of evidence indicate that ALKBH5 mainly inhibits the development of a variety of cancers." (PMID 34124065, 2021). "ALKBH5 inhibits cancer progression in an m6A-dependent manner via the glycolytic pathway as mediated by casein kinase 2, and promotes BC cell sensitivity to cisplatin." (PMID 35087575, 2021). "In other types of cancer, ALKBH5 and FTO also participate in many pathological and biological activities, referring to proliferation, apoptosis, migration, invasion and metastasis." (PMID 34895230, 2021). "Analysis of TCGA, MTB8,24, and CCLE databases revealed that ALKBH5 mRNA expression was consistently higher in KL cancer tissues or cells, and negatively correlated with LKB1 expression." (PMID 34016959, 2021). "In different cancers, ALKBH5 was up-regulated or down-regulated, and played an oncogenic or tumor suppressive role in breast cancer, gastric cancer, and colon cancer." (PMID 34103054, 2021). "FTO and ALKBH5 inhibit proliferation by regulating cell migration, invasion, and metastasis in some cancer cells." (PMID 34630412, 2021). "Experimental analysis has shown that ALKBH5 facilitates the proliferation and tumorigenicity of cancer stem cells by interacting with lncRNA FOXM1-AS." (PMID 35004679, 2021). "At present, some scholars have discovered that ALKBH5 regulates epithelial-mesenchymal transition and angiogenesis to promote cancer progression." (PMID 34150745, 2021). "In support of this idea, we identified the ALKBH5-m6A-YHTDF2 axis as a targetable molecular pathway to treat this aggressive cancer." (PMID 34016959, 2021). "The communication between ALKBH5 and long non-coding RNAs, miRNAs or mRNA is closely related with cancer cell proliferation, death, survival, and metastasis." (PMID 34103054, 2021). "In the field of human non-cancer research, ALKBH5 was involved in human reproductive system diseases via impacting on spermatogenesis and trophoblast invasion, or osteogenesis through AKT and NF-κB signaling pathways." (PMID 34103054, 2021). "Some reports have shown that ALKBH5 (ALKB homolog 5) has a strong correlation with the inhibition of cancer growth." (PMID 33744868, 2021). "A recent study has reported that the expression and function of ALKBH5 in different types of cancer are variable." (PMID 34079761, 2021). "Recently, the m6A demethylase ALKBH5 was reported to be induced by hypoxia to participate in the regulation of cancer development." (PMID 34218271, 2021). "ALKBH5 impaired cancer growth and metastasis in vivo by decreasing the expression and activity of YAP." (PMID 34211849, 2021). "ALKBH5, an m6A demethylase, can erase m6A mRNA modification and contribute to the progression of carcinomas." (PMID 33428593, 2021). "ALKBH5 enhances NANOG expression by abating m6A modification and accelerates the amplification of BCSCs in hypoxic microenvironment, illustrating the cancer‐promoting function of ALKBH5 in BC." (PMID 33029866, 2020). "This kind of communication between ALKBH5 and different RNAs was importantly related with cancer cell proliferation, apoptosis, death, survival, migration, invasion, metastasis and so on." (PMID 32742194, 2020). "According to recent studies, ALKBH5 plays an important role in the occurrence and development of cancer in human." (PMID 32106857, 2020). "Several recent studies highlighted the vital roles of FTO and ALKBH5 in cancer progression by regulating the stability and functions of some key ncRNAs." (PMID 32209098, 2020). "The PI3K/AKT/mTOR pathway has been implicated in the development of various types of cancer regulated by m6A proteins, including METTL3/WTAP in AML, METTL3 in RCC/PDAC, ALKBH5 in EOC, and FTO in melanoma and EC." (PMID 32513173, 2020).
cancer (continued). "The two key demethylases, FTO and ALKBH5, were also involved into the regulation of cancer progression as mRNA handlers." (PMID 32209098, 2020). "ALKBH5 was also connected with human non-cancer, such as reproductive system diseases and the process of ossification." (PMID 32742194, 2020). "ALKBH5 acts as a candidate oncogene, inhibiting cancer autophagy through miR-7 and BCL-2, eventually activating an EGFR-PI3K-AKT-mTOR signaling pathway." (PMID 32513173, 2020). "In the field of human non-cancer research, ALKBH5 was found to be dysregulated in human reproductive system diseases and osteogenic progression." (PMID 32742194, 2020). "Although both FTO and ALKBH5 belong to the AlkB family, they have differing substrate specificity for human cancers." (PMID 32296573, 2020). "Human AlkB homolog H5 (ALKBH5) is a primary m6A demethylase, which is dysregulated and acts as a biological and pharmacological role in human cancers or non-cancers." (PMID 32742194, 2020). "Low levels of ALKBH5 and FTO mRNA were associated with reduced overall as well as cancer-specific survival after nephrectomy." (PMID 33364952, 2020). "In this review, we summarized the current evidence on ALKBH5 in diverse human cancers or non-cancers and its potential as a prognostic target." (PMID 32742194, 2020). "Surprisingly, despite high expression of FTO/ALKBH5 in cancer tissue, the level of N6meA was also significantly elevated, in comparison to normal tissue." (PMID 31519943, 2019). "In the cancer tissue, we observed a similar correlation involving ALKBH5-FTO, ALKBH3-ALKBH5, and ALKBH1-ALKBH5, but also noted that the level of ALKBH2 was correlated with that of ALKBH5 and ALKBH1 with ALKBH3." (PMID 31519943, 2019). "Earlier studies have revealed the critical role of m6A regulators, particularly METTL3, METTL14, FTO and ALKBH5 in driving cancer progression and metastasis." (PMID 31069256, 2019). "It has been shown that silencing either METTL14 or ALKBH5 leads to cancer growth inhibition, a deregulation of the transforming growth factor– β signaling pathway, and epithelial-to-mesenchymal transition." (PMID 30654440, 2019). "Our findings reflect a discrepancy in FTO/ALKBH5 action as the demethylase regulating N6meA level in mRNA in normal vs cancer cells." (PMID 31519943, 2019). "The expression of ALKBH5 was significantly higher in cancer samples in advanced stages (stage III/IV) as compared to those in the early stages (stage I/II) disease (P < 0.05)." (PMID 30987661, 2019). "NANOG, a pluripotency factor functioning in the maintenance and specification of cancer stem cells, is demethylated by ALKBH5 at an m6A residue in the 3′ UTR." (PMID 30149601, 2018). "Furthermore, ALKBH5 is aberrantly expressed in various cancers, where its expression can either promote or inhibit tumorigenesis depending on the cancer type 49." (PMID 39990235, 2025). "Beyond cancer, ALKBH5 also modulates MDSC function in autoimmune diseases." (PMID 41562066, 2025). "However, Alkbh5 has also been demonstrated to possess significant pro-tumorigenic functions: it enhances cancer stem cell properties and immune evasion by stabilizing Snai2117, and its target, Linc02551, similarly drives HCC growth and metastasis." (PMID 41208876, 2025). "The m 6A RNA demethylase ALKBH5 shows opposite effects in different cancer species." (PMID 40483535, 2025). "Furthermore, ALKBH5 is an endogenous m6A demethylase, whose knockdown or overexpression led to an increase or decrease of several critical oncogenic RNA m6A in cancers." (PMID 40830264, 2025). "There is evidence that ALKBH5 can influence cancer immunity." (PMID 39781264, 2025). "Beyond cancer, ALKBH5 also regulates macrophage functions in metabolic diseases." (PMID 41562066, 2025).
cancer (continued). "In recent years, many inhibitors that target RNA modifications, such as small-molecule inhibitors of FTO and ALKBH5, which inhibit immune escape from tumors by targeting m6A modifications to inhibit the growth of many cancers, have been developed and investigated in clinical studies." (PMID 40360483, 2025). "ALKBH5-mediated m6A modification plays a crucial role in various human cancers." (PMID 39465506, 2025). "Thus, although many reports indicate that ALKBH5 functions in a cancer‐suppressive manner, it has also been reported to be cancer‐promoting in some cancer types." (PMID 40448344, 2025). "This suggests that the alteration of ALKBH5 expression during erastin-induced ferroptosis of cancer cells might be a concomitant phenomenon." (PMID 39800682, 2025). "Interactions between ALKBH5 and reader proteins in human cancers." (PMID 40958857, 2025). "The clinical relevance of this pathway is increasingly evident, as aberrant expression of m6A regulators such as METTL3, FTO, ALKBH5, or IGF2BPs correlates with poor prognosis, advanced disease stage, therapy resistance and immune evasion, in multiple cancer types." (PMID 41228380, 2025). "Therefore, future studies are needed to validate the robustness and generalizability of ALKBH5 as a biomarker in larger, multi-cancer clinical cohorts, integrating multi-omics data with immunotherapy follow-up." (PMID 41562066, 2025). "All evidence suggests that the role of ALKBH5 in the prognosis of cancers and biofunction might be context dependent." (PMID 39781264, 2025). "Furthermore, ALKBH5 is recognized as an oncogene in cancer progression, contributing to cellular resistance to chemotherapy." (PMID 39465506, 2025). "Immunofluorescent assay presented that the gRNAs of HDAC6 combined with dCas13b‐ALKBH5 could significantly increase the cilia length of cancer cells." (PMID 39535388, 2025). "The inhibition of Alkbh5 was found to enhance the efficacy of cancer immunotherapy." (PMID 39759516, 2024). "Moreover, targeting RBPs (such as HuR, LIN28, MSI and ALKBH5) has been identified as an effective therapeutic approach for cancer treatment." (PMID 37935976, 2024). "However, the paradoxical role of ALKBH5 in different cancers is evident, as it positively regulates PD‐L1 expression in intrahepatic cholangiocarcinoma." (PMID 38545841, 2024). "Immunofluorescence revealed reduced p-STAT3 expression in ALKBH5-knockdown cancer cells." (PMID 38872221, 2024). "ALKBH5 may also indirectly regulate PD-L1 expression via the m6A modification of other mRNAs in cancer cells." (PMID 38872221, 2024). "ALKBH5 inhibitors have also been developed and tested against cancer cells." (PMID 39661414, 2024). "The m6A erasers FTO and ALKBH5 also mediate chemoresistance in cancer." (PMID 38545841, 2024). "This indicated that ALKBH5 may be posttranscriptionally regulated in various cancer types and thus results in its controversial effects." (PMID 38098223, 2024). "WTAP and ALKBH5 showed varied abundance across different cancer types analyzed." (PMID 38665783, 2024). "RIP–qRT-PCR confirmed the binding of ALKBH5 to JAK2 mRNA in cancer cells." (PMID 38872221, 2024). "Moreover, the mRNA expression of FTO and ALKBH5 in the PB of MC38 cancer model mice was also decreased compared with those in the PB of the control mice (P < 0.05)." (PMID 38439072, 2024). "ALKBH5, as a potential target for cancer therapy, holds significant research value." (PMID 39295872, 2024). "AlkB homolog 5 (ALKBH5) could be demethylated by N6 -methyladenosine (m6A) and this process has been found to promote cancer development in humans and enhance the stability of USP1 mRNA." (PMID 39048945, 2024). "ALKBH5 regulates the progression of cancers in a cell type-dependent manner." (PMID 38252669, 2024).